PLK1 (polo like kinase 1)
Diseases named in the same sentence as PLK1 in open-access papers (continued):
Sharing a sentence is not in itself a finding about the gene and the disease.
cancer (continued). "PLK1 regulates processes such as centrosome maturation, bipolar spindle formation, kinetochore-microtubule attachment, and cytokinesis, and its dysregulation has been consistently linked to mitotic errors and chromosomal missegregation in a variety of cancer types." (PMID 40430225, 2025). "Thus, in some patients receiving PLK1 inhibitors during cancer treatment, the risk of infection with invading microorganisms may be increased due to the impaired ability of the TLR recognition system to sense and initiate a cytokine response." (PMID 40612941, 2025). "However, PLK1 gene polymorphisms (such as rs27770, rs40076, rs57973275) may regulate cancer risk and treatment response by affecting its expression, mRNA stability, or function." (PMID 40612941, 2025). "Cancer cells may also develop resistance by mutating the PLK1 kinase domain." (PMID 38780513, 2024). "Additionally, PLK1 overexpression is commonly linked to a poor cancer prognosis." (PMID 39085197, 2024). "In addition, Akdeli and colleagues identified rs27770 as a functional polymorphism that might affect cancer risk, progression and pharmacological resistance by modulating the secondary structure and stability of PLK1 mRNA." (PMID 37447165, 2023). "Additionally, PLK1 responds to DNA damage, which is associated with cancer drug resistance." (PMID 38201556, 2023). "Furthermore, PDK1 mediates chemoresistance in different cancer cell types by the activation of several oncogenic pathways, namely Polo-like kinase-1 (PLK1)- myelocytomatosis (MYC) Axis, Yes-associated Protein (YAP)/Hippo Pathway, and the serum and glucocorticoid inducible protein kinase (SGK) Axis." (PMID 36076967, 2022). "In addition, since the R293C/H missense mutation occurred in the Pkinase domain of PLK1 protein, we speculated that the R293C/H missense mutation could lead to the genesis and progression of cancers by changing the Pkinase activity of PLK1 proteins." (PMID 36618405, 2022). "However, the exact mechanism that is responsible for this arrest and associated apoptosis in Plk1-depleted cancer cells remains unknown." (PMID 34887439, 2021). "Moreover, it has been demonstrated that polymorphisms in PLK1 influence its expression, therefore they could potentially affect cancer risk and progression." (PMID 31521144, 2019). "Thus, PLK1 is a potential anticancer therapeutic target, and aberrant expression of PLK1 appears to be a considerable causative factor for human diseases such as cancer." (PMID 30367032, 2018). "Furthermore, the GDSC data analysis showed that the IC50 values of both GW84368 and BI-2536 were negatively associated with the immune scores of cancer cells (Spearman correlation, P<0.01), again suggesting that elevated immune activities increase the sensitivity of cancer cells to PLK1 inhibitors." (PMID 30631355, 2018). "Additionally, PLK1 overexpression is associated with poor prognosis in cancer patients." (PMID 29383106, 2017). "Thus, identification of putative Plk1-dependent novel substrates in context to cancer and cell-cycle process will unravel the underlying molecular mechanisms and may prove significant for the assessment of multi-targeted drug candidates." (PMID 23967120, 2013).
cancer (continued). "Recently, the inhibition of PLK1 with antibodies, antisense oligonucleotides (ASOs), small interfering RNA (siRNA), or dominant negative mutants that suppress tumor growth by causing increased apoptosis have gained much interest as therapeutic options to treat cancer." (PMID 24159333, 2013). "Interestingly, overexpression of Plk1 is associated with tumor development and could serve as a prognostic marker for many cancers." (PMID 19161615, 2009). "PLK1 has been shown to have carcinogenic properties in many cancers; however, its role in the pathology of LUAD and its relationship with clinical features are rarely reported." (PMID 41556056, 2026). "The compelling oncogenic functions of PLK1 across cancer types have spurred the development of targeted inhibitors to explore its therapeutic potential." (PMID 41556056, 2026). "PLK1, a critical oncogenic kinase overexpressed in various cancers, has emerged as a promising therapeutic target, with several inhibitors (e.g., BI-2536) that previously underwent clinical trials for solid tumors, including NSCLC." (PMID 41539998, 2026). "Polo-like kinase 1 (PLK1) is a master regulator of mitosis and a well-established driver of cancer progression." (PMID 42054108, 2026). "Analysis of TCGA and GTEx databases revealed differential PLK1 expression across various cancer types." (PMID 41556056, 2026). "Considering the diverse functions of PLK1 and its other family members, there are still major challenges in using direct PLK1 inhibitors for cancer therapy and, as such, alternative strategies are needed." (PMID 40347943, 2025). "In the current study, we showed that G2/M blockers such as barasertib (AZD1152, AukB inhibitor) or volasertib (BI 6727, a PLK1 inhibitor) are promising anti-cancer approaches in resistant cells." (PMID 40764324, 2025). "Several cell cycle proteins, including D- and E-type cyclins, CDKs (CDK2, CDK4, CDK6), PLK1, and Aurora kinases, are commonly overexpressed in cancers and contribute to tumor development and progression." (PMID 41154590, 2025). "Beyond its role in cancer, PLK1 has been identified as an important regulator of smooth muscle contraction." (PMID 41227386, 2025). "Due to its key roles in mitosis and DNA damage checkpoint and its overexpression in cancer, PLK1 is considered as a potential therapeutic target for cancer treatment." (PMID 40852028, 2025). "Wang and colleagues, through cell and animal model studies, suggested that ST8SIA6-AS1 promotes malignant proliferation of KRAS^G12C mutant cancers by activating the Aurora A/PLK1/c-Myc pathway." (PMID 41282486, 2025). "In conclusion, this study provides essential insights into BPNMs as PLK1 inhibitors and presents a viable strategy for their application in cancer treatment, thereby paving the way for the clinical use of BPNMs as cancer chemotherapeutics." (PMID 41476654, 2025). "Polo-like Kinase 1 (PLK1) is a serine/threonine protein kinase that has emerged as a next generation target in the treatment of cancer." (PMID 40615690, 2025). "The results indicated that compound 150441 effectively inhibited the expression of Aurora A and cyclin B1 and the activation of PLK1, CDK1, and CDC25C, causing cancer cell arrest in the G2 phase." (PMID 40126184, 2025). "According to the literature, PRC1 is regulated by PLK1-dependent phosphorylation, and inhibition of PLK1 or direct targeting of PRC1 can lead to its aberrant expression, subsequently causing cytokinesis defects and cancer progression." (PMID 41187218, 2025). "Recent studies have shown that PLK1 is also involved in the development of malignant tumors, including LC." (PMID 41460629, 2025). "Elevated Plk1 activity significantly inhibits cell death pathways through the processes of autophagy and apoptosis, thereby promoting cancer cell proliferation." (PMID 40166466, 2025). "This has positioned PLK1 as a highly promising therapeutic target for the treatment of a variety of cancers." (PMID 40190550, 2025).
cancer (continued). "PLK1 inhibition induces mitotic arrest and apoptosis in cancer cells, highlighting its potential as a therapeutic target." (PMID 40270498, 2025). "Through an integrative approach combining molecular biology, metabolomics, and functional assays, we aim to elucidate how PLK1 reprograms serine metabolism to drive cancer progression." (PMID 40475404, 2025). "PLK1 has been identified as a new potential therapeutic target in cancer, and onvansertib is an oral, third-generation PLK1 inhibitor in clinical development in both hematological and solid tumors." (PMID 40565172, 2025). "PLK1 has been identified as a potential new target for cancer therapy, with several PLK1 kinase inhibitors developed as anti-cancer drugs currently under evaluation in clinical trials." (PMID 40487391, 2025). "We also evaluate its potential as a cancer therapy tool by applying eCas12f1 to disrupt PLK1 gene to reduce cell survival and BRAF gene with V600E mutation for targeted therapy." (PMID 39809780, 2025). "PLK1 inhibition induces cancer cell death but, at the same time, upregulates the programmed cell death protein PD-L1 expression in the surviving cancer cells." (PMID 40124344, 2025). "Accumulating evidence has revealed that PLK1 is highly elevated in multiple cancer types and correlated with worse patient survival." (PMID 41284701, 2025). "We show that various EDs, including Benzo[a]pyrene, can stably bind to PLK1 and, through the upregulation of PLK1 protein expression, potently drive cancer cell proliferation, migration, and invasion." (PMID 41415207, 2025). "Volasertib (BI-6727) is a selective PLK1 inhibitor that has shown promise as an effective cancer therapy in early-phase clinical trials with side effects being reversible and manageable." (PMID 39831777, 2025). "PLK1 has also regularly been observed to be overexpressed in cancer tissues, resulting in its appeal as a putative target for cancer therapies." (PMID 41329781, 2025). "Plk1 is often overexpressed in aggressive cancer types but is mainly studied for its role in mitosis entry." (PMID 39883014, 2025). "In particular, gold nanorods (Au NRs) functionalized with zinc(II)-dipicolylamine are utilized as carriers for siPLK, which specifically inhibits the expression of polo-like kinase-1 (PLK1) in cancer cells, thereby forming innovative NPs." (PMID 40448105, 2025). "Based on STRING analysis, MEIKIN is implicated in chromosome segregation and cell cycle regulation, through interactions with key proteins such as SGO1, SGO2, PLK1, and ESPL1, all of which are known to play critical roles in cancer-associated pathways." (PMID 41463182, 2025). "Polo-like kinase 1 (PLK1) coordinates biosynthesis during cell cycle progression and promotes cancer cell growth by directly increasing G6PD phosphorylation and activating the PPP." (PMID 39859324, 2025). "PLK1 is highly expressed in many human cancer types, including colorectal, breast, esophageal and gastric, endometrial, head and neck, and lung cancer." (PMID 40615690, 2025). "While Polo-like kinase 1 (PLK1) inhibitors have shown promise in cancer treatment, current inhibitors face challenges with toxicity and narrow therapeutic windows, highlighting the need for more effective and safer PLK inhibitors." (PMID 40190550, 2025). "In particular, volasertib (BI-6727) is a selective PLK1 inhibitor that has shown promise as an effective cancer therapy in early-phase clinical trials." (PMID 39831777, 2025). "By unraveling this molecular crosstalk, we aim to develop new therapeutic strategies targeting PLK1-mediated metabolic pathways in advanced cancers." (PMID 40475404, 2025). "Inhibition of Plk1 results in mitotic arrest and aberrant cell division leading to cell death, making Plk1 an attractive target for cancer therapy." (PMID 39971898, 2025). "Although protein stability of PLK1 can be regulated by DUBs in different cancers, the deubiquitination network of PLK1 in PDAC needs to be further defined." (PMID 40517136, 2025).
cancer (continued). "By combining comprehensive genome-wide screening with in-depth validation, our study highlights IGF2BP2 as a compelling candidate for targeted therapy in PLK1-overexpressing cancers." (PMID 40347943, 2025). "Despite PLK1's strong expression during mitosis and in many distinct forms of cancer, lower levels of PLK1 in cancer cells disturb cell proliferation and death." (PMID 40925573, 2025). "We observed significantly increased sensitivity to the PLK1 inhibitors GW843682X and BI-2536 in cancer cell lines with FA pathway mutations compared with those with WT FA genes." (PMID 40111122, 2025). "Recruiting PLK1 to the central spindle during anaphase is necessary for its function in promoting cancer cell proliferation, which is achieved by binding to microtubule-associated protein regulating of cytokinesis (PRC1) located in the spindle." (PMID 40355412, 2025). "A recent search of Clinicaltrials.gov for “Cancer and PLK1”, indicates 29 studies, 9 of which are listed as recruiting." (PMID 40379873, 2025). "For example, phosphorylation of the human PLK1 protein at S137 promotes cancer cell survival in response to mitochondrial dysfunction, while the phosphorylation at T210 is required for enhancing neuroprotective autophagy." (PMID 40581078, 2025). "PLK1 plays a key role in the biosynthesis of cancer cells by promoting the formation of glucose-6-phosphate dehydrogenase (G6PD) active dimers, interacting with them and directly phosphorylation, thereby activating the pentose phosphate pathway (PPP)." (PMID 40612941, 2025). "Among them, PLK1 is an attractive anticancer drug target owing to its overexpression in various human cancers." (PMID 40871048, 2025). "Recent studies have found that changes in certain biomarkers can alter the sensitivity of cancer cells to PLK1 inhibitors." (PMID 41458961, 2025). "While lower concentrations of C4 and C9 compounds suppressed PLK1 overexpressing cancer cells more effectively, compound C4 showed the best in vivo pharmacokinetic (PK) profile of the tested IGF2BP2 inhibitors." (PMID 40347943, 2025). "Among the 5 family members identified thus far, PLK1 has been studied in greater detail and is overexpressed in several cancers, such as melanoma, head and neck squamous cell carcinoma, and various other solid tumors." (PMID 40547482, 2025). "Western blot experiments confirmed the reduced expression of CDK1, CCNB1, and PLK1 in KIF2C knockdown cancer cells at the protein level." (PMID 41333555, 2025). "siRNA targeting the polo-like kinase-1 (PLK1) gene impairs cancer cell proliferation, leading to mitotic arrest and apoptosis." (PMID 40943628, 2025). "PLK1 inhibitors are emerging anticancer agents that are being tested as monotherapy and combination therapies for various cancers." (PMID 39658088, 2025). "Aberrant PLK1 activity promotes cancer cell proliferation and invasion through overriding mitotic checkpoints, suppressing cell apoptosis, inducing cellular stress, and facilitating epithelial-mesenchymal transition (EMT)." (PMID 41458961, 2025). "In this study, we constructed a plk1 core genomic instability network in cancer by integrating previously known mechanisms and the nine essential biological processes necessary for maintaining genomic stability." (PMID 40430225, 2025). "These NPs effectively inhibit PLK1, thereby reducing the viability and proliferative activity of cancer cells." (PMID 40448105, 2025). "This combined disruption of the major energy-producing pathway in PLK1-overexpressing cancer cells impairs energy metabolism, which in turn severely affects their viability." (PMID 40347943, 2025). "A certain intracellular ROS level is required for Plk1 to exert its biological functions, and inhibiting the production of ROS can partially change the anti-proliferative activity of Plk1 in cancer cells." (PMID 40166466, 2025).
cancer (continued). "Our findings corroborate this established role, demonstrating that PLK1 is highly expressed in most cancer types and that its overexpression is significantly correlated with poor prognosis in PCa patients." (PMID 41415207, 2025). "Analysis of the TCGA dataset identified PLK1 as one of the proliferation-related kinases highly expressed in cancers with chromosome 9p copy number gains (CNGs) involving PD-L1." (PMID 40612941, 2025). "PLK1 is overexpressed in various cancers, and growing evidence supports coupling of PLK1 to tumorigenesis, tumor progression, and chemoresistance." (PMID 41022752, 2025). "Consistent with this, pharmacological inhibition of IGF2BP2 severely impacts the viability of PLK1-overexpressing cancer cells addicted to higher metabolic rates." (PMID 40347943, 2025). "This multistage mechanism effectively delivers siRNA against polo-like kinase-1 (siPLK-1), a mitotic regulator overexpressed in cancer cells, and docetaxel to tumors to downregulate expression of PLK-1 and inhibit tumor growth." (PMID 40856125, 2025). "PLK1 inhibitors, therefore, have become a promising line of treatment in cancer therapy, especially for tumors with a high mitotic index." (PMID 40547482, 2025). "These metabolic alterations highlight the therapeutic potential of targeting PLK1-mediated metabolic vulnerabilities in cancer therapies." (PMID 40475404, 2025). "Initially, the nsSNPs of PLK1 were retrieved for different cancer phenotypes utilizing a large set of cancer databases." (PMID 41404416, 2025). "Inhibitors targeting PLK1 or WEE1 are emerging as promising therapeutic agents for cancer treatment that disrupt the critical G2/M checkpoint, leading to cancer cell death." (PMID 39994376, 2025). "PLK1 is overexpressed in many types of cancer, including ovarian cancer, and its overexpression has been associated with poor patient outcome and with resistance to therapy." (PMID 40565172, 2025). "This reprogramming highlights PLK1’s dual role in cell cycle regulation and metabolic control, positioning it as a central orchestrator of cancer metabolism." (PMID 40475404, 2025). "Downregulation of Plk1 by small molecular inhibitors or siRNA significantly reduces cell invasion and migration in multiple types of cancer cells." (PMID 40166466, 2025). "PLK1 is overexpressed in various cancers, including invasive breast carcinoma, liver carcinoma, colon adenocarcinoma, lung squamous cell carcinoma, prostate adenocarcinoma, gastric cancer, ovarian cancer, and melanoma." (PMID 39859203, 2025). "Dysregulation of PLK1 is highly frequent in various malignancies and is correlated with poor prognosis in many cancers." (PMID 40496862, 2025). "Inhibitors targeting PLK1 have been explored as potential treatments for advanced PCa, aiming to disrupt mitotic processes essential for cancer cell proliferation." (PMID 41402347, 2025). "Among the proliferation‐associated genes analyzed—including MKI67, PCNA, MCM2–7, MAP17 (PDZK1IP1), and PLK1—many demonstrated strong positive correlations with C1GALT1 expression in cancers such as pancreas, bladder, breast, stomach, prostate, and liver." (PMID 40548474, 2025). "Given its central role in cell cycle regulation and its elevated expression in various cancers, PLK1 has emerged as a promising target for cancer therapy." (PMID 40612941, 2025). "For example, in vitro, tetraploid cancer cells are more susceptible than diploid cancer cells to anti-mitotic stabilizer paclitaxel or inhibitors of a mitotic kinase MPS1, Plk1, or a mitotic kinesin motor protein Kifl18A (for review)." (PMID 40117022, 2025).